DYRK1B (dual specificity tyrosine phosphorylation regulated kinase 1B)
Diseases named in the same sentence as DYRK1B in open-access papers (continued):
Sharing a sentence is not in itself a finding about the gene and the disease.
cancer (continued). "Our data are in agreement with other studies that have implicated Dyrk1B in canonical and non-canonical Shh pathway in many cancers." (PMID 38294527, 2024). "Collectively, the strategy of targeting Dyrk1A, Dyrk1B, and Clk1 simultaneously with a small molecule could offer significant benefits in tackling the complex nature of cancer." (PMID 38893153, 2024). "Furthermore, Dyrk1B maintains the quiescence of cancer stem cells (CSCs) and regulates their maintenance under normoxic or hypoxic conditions." (PMID 38675189, 2024). "The gain of mesenchymal traits may explain the increase in chemoresistance und migratory capacity that has been observed in several cancer cell types with elevated expression of DYRK1B." (PMID 39482615, 2024). "Further profiling of DYRK1B-overexpressing cells revealed transcriptional changes that are characteristic for the mesenchymal conversion of epithelial cells, including the upregulation of genes that are related to cancer cell invasion and metastasis." (PMID 39482615, 2024). "Recently, Dyrk1B has emerged as a novel therapeutic target for cancer." (PMID 38675189, 2024). "Notably, it has been reported that activation of the MAP/ERK2 pathway activates DYRK1B kinase function in cancer cells and further phosphorylates its downstream proteins, such as FOXO126,27,52." (PMID 37120440, 2023). "More interestingly, DYRK1B can enhance a zinger finger protein, glioma associated transcription factor (GLI1), to increase canonical Hedgehog (Hh) signaling, which is essential for cancer development and stemness." (PMID 34830933, 2021). "Although the efficacy of AZ191 and transfection in each cell line might be variable, these results imply that the kinase activity of DYRK1B might be partially involved in cancer cell proliferation and metastatic characteristics." (PMID 34830933, 2021). "Together with our results, these findings imply that DYRK1B might have a different route to regulate cell proliferation in cancer cells." (PMID 34830933, 2021). "Our results may provide a platform to identify potential targets for cancer therapy, and, hopefully, present DYRK1B as therapeutic target for TNBC." (PMID 34830933, 2021). "However, our screening results showed that only silencing DYRK1B has selective effects on cancer cell suppression in TNBC cells compared to normal breast M10 cells." (PMID 34830933, 2021). "The RAS-DYRK1B axis was proposed to participate in both autocrine and paracrine Hh signaling in PDAC, although the role of DYRK1B in the regulation of Hh signaling in cancer remains controversial, as it has been attributed opposite functions within this signaling pathway." (PMID 32751160, 2020). "The functional interaction of DYRK1B with signaling pathways involved in cancer cell proliferation has been explored, assessing both the fluctuations in DYRK1B expression upon the perturbation of growth pathways and the output provoked by DYRK1B depletion in cancer cell lines." (PMID 32751160, 2020). "We verified the findings made in fibroblasts by overexpressing DYRK1B in human cancer cells." (PMID 27903983, 2017). "Interestingly, knocking down Dyrk1B induced apoptosis and increased sensitivity of human cancer cells to therapeutic agents." (PMID 26307683, 2015). "This suggests that activation of Mirk/Dyrk1B kinase in the deregulated cancer cells may be mediated by tyrosine autophosphorylation, although further study is required." (PMID 23311607, 2013). "As a result, the quiescent cancer cells depleted of Mirk/Dyrk1B out of G0 entering into the cell cycle may enhance cancer cell kill by chemotherapeutic drugs or radiation, while having less effect on normal tissues in which Mirk/Dyrk1B levels are quite low." (PMID 23311607, 2013). "In the past decade, growing evidence has demonstrated that knockdown Mirk/Dyrk1B could induce cell apoptosis and increase sensitivity of various human cancer cells to conventional chemotherapeutics." (PMID 23311607, 2013).
cancer (continued). "Moreover, Mirk/Dyrk1B, through regulating cyclin D turnover and p27 stabilization, functions independently and additively to regulate the exit of cancer cells from quiescence G0 or early G1 into S and G2/M of cell cycle." (PMID 23311607, 2013). "Furthermore, the knockdown Mirk/Dyrk1B by small interfering RNA (siRNA) induced cell apoptosis and increased sensitivity of human cancer cells to conventional chemotherapeutics in vitro." (PMID 22159921, 2012). "Moreover, a small-molecule DYRK1B-directed therapy combined with mTOR inhibition and conventional chemotherapy restricted the growth of established tumors and extended survival in an aggressive murine PDAC mouse model, significantly extending the understanding of DYRK1B as an anti-cancer target." (PMID 39863750, 2025). "Increased DYRK1A expression was described in Down syndrome, while elevated DYRK1B levels were reported in solid tumors, such as gastrointestinal tumors or lung cancer, and acts as a negative cell cycle regulator in many tissues (e.g., by enhancing the resistance of cancer cells to chemotherapy)." (PMID 40002350, 2025). "In addition to its influence on the cell cycle, DYRK1B contributes to cancer cell resistance against anticancer drugs by facilitating the repair of DNA double-strand breaks, and enhances tolerance to redox stress through the upregulation of antioxidant enzymes." (PMID 39482615, 2024). "Thus, the pharmacological inhibition of Dyrk1B could be beneficial in cancer therapy targeting mTOR signaling." (PMID 38675189, 2024). "In addition, Dyrk1B cross-talks with the Hedgehog/Gli pathway, by inhibiting ‘canonical’ and enhancing ‘non-canonical’ Hh signaling, are implicated in cancer." (PMID 38675189, 2024). "In addition, cancer cell survival is enhanced by the antiapoptotic activities of Dyrk1B." (PMID 38893153, 2024). "Family member DYRK1B has demonstrated a strong increase when tumor cells exit the cell cycle upon mitogen deprivation or the pharmacological inhibition of proliferative pathways in different cancer cell types (breast, colon carcinoma, melanoma, pancreatic, and ovarian cancer cells)." (PMID 36835173, 2023). "In summary, and in contrast to the controversial role of DYRK1A in cancer, clear oncogenic facets have been attributed to DYRK1B, acting as a prosurvival factor that could help cancer cells survive in suboptimal growth conditions and preventing chemotherapeutic-induced DNA damage and apoptosis." (PMID 32751160, 2020). "In this context, DYRK1B overexpression may help maintain a reversible quiescent state or inhibit cancer cell proliferation, while DYRK1B reduction can drive cell cycle entry in quiescence (by reducing the DYRK1B expression in PDAC or by DYRK1B inhibition in CRC cell lines)." (PMID 32751160, 2020). "From a therapeutic point of view, the fluctuating kinetics of GLI1 levels following a DYRK1B inhibition are problematic as suboptimal or short-term treatments with DYRK1B antagonists might result in concomitant upregulation of oncogenic GLI1 in cancer cells." (PMID 27903983, 2017). "Therefore, Our study along with others suggests that MAPK/ERK signaling may inhibit Mirk/Dyrk1B transcription and functions in human cancer cells." (PMID 23311607, 2013). "Mirk/Dyrk1B contributes to G0 arrest by destabilization of cyclin D1 and stabilization of p27kip1 to maintain the viability of quiescent human cancer cells, and it could be negatively regulated by mitogenic-activated protein kinase (MAPK)/extracellular signal-regulated kinase (ERK) signaling." (PMID 23311607, 2013). "Thus, an increase in cisplatin toxicity selectively in cancer cells could result from further increasing the cisplatin-elevated ROS levels by targeting antioxidant genes upregulated in cancers such as those mediated by the kinase Mirk/dyrk1B." (PMID 21559261, 2011).
cancer (continued). "Instead, it additionally appears that DYRK1B exerts potent cell-extrinsic functions in the TME, thereby creating an immunological safe haven and shielding cancer cells from the host immune system." (PMID 39863750, 2025). "In the present study, we scrutinized the regulatory pathways modulating DYRK1B expression relative to DYRK1A in PANC-1 and A549 cancer cell lines across varying conditions." (PMID 39397076, 2024). "Inhibition of DYRK1B reduces GLI1 expression, offering a potential therapeutic target for GLI1-dependent cancers resistant to SMO inhibitors." (PMID 39568072, 2024). "Overall, the current evidence regarding the regulation of DYRK1B expression presents several unresolved questions, specifically regarding the diverging expression patterns of DYRK1B and DYRK1A among various human cancers." (PMID 39397076, 2024). "In summary, our findings indicate that the expression of DYRK1A and DYRK1B is differentially regulated in cancer cells and reveal that the kinase inhibitor XMU-MP-1 increases DYRK1B expression likely through off target inhibition of Aurora kinases." (PMID 39397076, 2024). "Specifically, the effects of DYRK1B in A549 cells resemble the effects of TGFβ, which is well characterized as an inducer of EMT in A549 and other carcinoma cell lines." (PMID 39482615, 2024). "Dual-specificity tyrosine-phosphorylation-regulated kinase 1B (DYRK1B) was identified as a critical player in both sensitive and resistant cancers to SMO inhibitors." (PMID 35163655, 2022). "Given the induction of cancer cell dormancy by DYRK1B in various cancer types, we also investigated the interactions between CIRBP and DYRK1B as well as the resulting impacts of these interactions on the tumourigenesis and chemoresistance of PDAC cells." (PMID 34490236, 2021). "Taken together, we propose that a dual targeting approach combining a DYRK1B antagonist with an inhibitor of the PI3K/mTOR/AKT pathway has a pronounced impact on the GLI1 oncoprotein and exerts strong cytotoxic effects in cancer cells." (PMID 27903983, 2017). "In this investigation, we further show that inhibition of DYRK1B reduced BafA1-induced HCC cell death, supporting its role as a mediator of the anti-cancer effects of BafA1." (PMID 27845389, 2016). "DYRK1B, the closest homologue of DYRK1A, can act downstream of RAS to prevent autocrine and promote paracrine HH signaling in RAS mutant cancer cells." (PMID 26784250, 2016). "All together indicate the possible interaction between Mirk/Dyrk1B and MAPK/ERK signals in human cancer cells." (PMID 23311607, 2013). "Specifically, DYRK1B not only fosters cell-intrinsic processes like cell survival, chemoresistance, and disease recurrence, but it also upregulates TME and cancer cell-protective innate immune checkpoints and down-modulates anti-tumoral macrophage functionality." (PMID 39863750, 2025). "Rather than driving proliferation, increased levels of DYRK1B promote cell cycle exit and maintain cancer cells in a non-proliferating state (G0)." (PMID 39482615, 2024). "Following its discovery, several studies have used AZ191 in Dyrk1B targeted cancer therapy combined or not with other kinase inhibitors and/or chemo- and radio-therapy approaches." (PMID 38675189, 2024). "Moreover, Dyrk1B comprises a central mediator of Sonic hedgehog/Gli, PI3K/mTOR/AKT, and RAF/MEK/ERK signaling pathways in cancer." (PMID 38675189, 2024). "DYRK1B is the closest paralog of DYRK1A within the family, sharing a high degree of homology at the primary and secondary structure, with activities connected mostly to cancer development." (PMID 39405283, 2024). "Moreover, Dyrk1B up-regulates the expression of several antioxidant genes, e.g., superoxide dismutases 2 and 3 (SOD2, SOD3) and ferroxidase in cancer cell lines." (PMID 38675189, 2024). "Indeed, the usage of Dyrk1B inhibitor EHT5372 enhanced the toxicity of mTOR inhibitor RAD001 in pancreatic Panc1 and ovarian TOV21G, SKOV3, and OVCAR3 cancer cells." (PMID 38675189, 2024).
cancer (continued). "Given that RTKs are common targets in cancer therapy, the inhibition of DYRK1A (and its paralog DYRK1B) could be considered an element in combinatorial therapies to simultaneously target several deregulated RTKs." (PMID 32751160, 2020). "Furthermore, we introduce a novel small molecule DYRK1B inhibitor with potent in vitro and in vivo activity targeting GLI dependent cancer cells." (PMID 26784250, 2016). "All of above suggest that Mirk/Dyrk1B may mediate cell cycle and cell survival through interacting with MAPK/ERK pathway in human cancer." (PMID 23311607, 2013). "Regardless of the mechanism, the upregulation of DYRK1B in response to AURK or mTORC inhibitors may contribute to the development of cancer cell resistance to chemotherapeutic drug treatment." (PMID 39397076, 2024). "Thus, these novel scaffolds present a potential new avenue for therapeutic development targeting Dyrk I class in cancer, but they do not solve the problem of selectivity between Dyrk1A and Dyrk1B kinases." (PMID 38675189, 2024). "In line with previous findings, our current study shows that high expression of DYRK1B is correlated with disease-free survival in TNBC patients, supporting the notion that DYRK1B might serve as a drug resistant gene and results in recurrence of cancer cells." (PMID 34830933, 2021). "In light of these findings we hypothesized that targeting DYRK1B may represent a novel strategy to inhibit oncogenic GLI1 activity in cancer cells with non-canonical, SMO-independent GLI1 activation." (PMID 26784250, 2016). "Here, we demonstrate that expression of DYRK1B - but not its closely related paralog DYRK1A - is upregulated by cytostatic drugs (Actinomycin D, Doxorubicin) in multiple cancer cell lines." (PMID 41888523, 2026). "Likewise, MDA-MB-231 stably harbored shRNA against DYRK1B diminished DYRK1B expression and tumorsphere viability compared with the scrambled cells, suggesting DYRK1B is necessary for supporting anchorage independent cancer cell growth, but not for forming spheres." (PMID 34830933, 2021). "A recent review of DYRK1B has offered extensive information on this kinase, and thus, here, we will focus on those aspects of the kinase that are related to its role in cancer, which, unlike DYRK1A, point mostly to a prosurvival and protumorigenic role for DYRK1B." (PMID 32751160, 2020).
tumor (25 papers, 2011 to 2026). "Conversely, under normoxic conditions, the elevated expression of Dyrk1B leads to HIF2α destabilization, loss of glioma stemness, inhibition of tumor development, and a more favorable outcome for patients." (PMID 38675189, 2024). "For example: MDA-MB-231 and MDA-MB468 have wild type of BRCA1, whereas HCC1937 has mutated BRCA1, Thus, the protein levels of DYRK1B in tumor tissues and the regulation mechanisms of DYRK1B in tumors need further empirical verification." (PMID 34830933, 2021). "Since DYRK1B can promote cell cycle arrest and differentiation, such loss-of-function mutations suggest that any oncogenic properties of DYRK1B are, at best, context-dependent; indeed, they may even suggest tumour suppressor functions for wild-type DYRK1B." (PMID 26346493, 2016). "The amplification of this region with coherent DYRK1B overexpression was observed in other tumor types, suggesting that they may underlie the increase in DYRK1B expression, although this may also be provoked by transcriptional activation due to changes in the transcriptional profiles of tumor cells." (PMID 32751160, 2020). "Genetic ablation or pharmacological inhibition of DYRK1B changed the secretome of PDAC tumor cells to strongly attract macrophages into tumor sites via the overproduction of CCL5, CCL6, CXCL2, and MCSF." (PMID 39863750, 2025). "An unbiased analysis of data from The Cancer Genome Atlas (TCGA) showed increased DYRK1B mRNA levels in 9 out of 14 tumor types compared with matched healthy tissue samples." (PMID 39482615, 2024). "Under serum starvation and hypoxic conditions, Dyrk1B protein expression is upregulated in tumor cells, thereby mediating cell cycle arrest as a stress-survival mechanism." (PMID 38675189, 2024). "Numerous studies have documented an higher expression of DYRK1B in tumor samples than in normal tissue." (PMID 39482615, 2024). "It is conceivable that the observed upregulation of DYRK1B expression in 3D culture compared to 2D monolayer culture can be partially attributed to the extensive cell-cell contacts in tumour cell spheroids." (PMID 39397076, 2024). "The protein level of DYRK1B was significantly elevated on tumor tissues compared to that in normal (p < 0.001) or adjacent normal tissues (p = 0.034) of TNBC patients." (PMID 34830933, 2021). "Serum reduction of U87MG 2D cultures or multi‐cellular tumour spheroids induced a quiescent like state characterized by increased DYRK1B and p27, and decreased pRb and cyclin D1." (PMID 34708541, 2021). "We examined the expression of DYRK1B by IHC using a human lipomatous tumor tissue microarray (TMA) and human normal tonsil tissue as control." (PMID 29568347, 2018). "Several studies suggest that tumor cells expressing DYRK1B more heavily rely on its activity and that DYRK1B depletion compromises the ability to maintain quiescence." (PMID 29942794, 2018). "We first monitored the effect of DYRK1B inhibition on tumor-initiating spheroid formation of GLI1-dependent yet SMO-inhibitor resistant PANC-1 cells in 3D cultures." (PMID 26784250, 2016). "The kinase Mirk/dyrk1B is highly expressed in the vast majority of osteosarcomas and rhabdomyosarcomas and mediates their growth, as depletion of Mirk led to tumor cell apoptosis." (PMID 21559261, 2011). "DYRK1B is a serine/threonine kinase involved in tumor progression and cell proliferation." (PMID 39545598, 2024). "Notably, synergistic effects of Dyrk1B inhibition combined with chemotherapy have been reported in tumor cell killing." (PMID 38675189, 2024). "In addition to the cell-intrinsic functions, DYRK1B has recently been shown to regulate the tumor microenvironment by controlling the secretome of pancreatic cancer cells." (PMID 39482615, 2024). "Conclusions: our results suggest DYRK1B might be essential for promoting tumor progression and could be a theranostic target for TNBC." (PMID 34830933, 2021).